RNF43 (ring finger protein 43)
Diseases named in the same sentence as RNF43 in open-access papers (continued):
Sharing a sentence is not in itself a finding about the gene and the disease.
tumor (continued). "Although RNF43-based immune therapies suggested its clinical potential, the precise role of RNF43 mutation in tumor cells in immunotherapy remains to be clarified." (PMID 29293510, 2018). "Next generation sequencing found only the KRAS G12D and RNF43 G659Vfs*41 mutations were retained from the pre-treatment tumor in the treatment-resistant tumor." (PMID 30458888, 2018). "Only the KRAS G12D and RNF43 G659Vfs*41 mutations were retained from the pre-treatment tumor in the treatment-resistant tumor." (PMID 30458888, 2018). "RNF43 encodes a transmembrane protein exhibiting the function of ubiquitin E3 ligase and seems to act as a tumor suppressor." (PMID 29156578, 2017). "This is a surprising result given that RNF43 physically interacts with very few gene products and in general, is associated as a tumor suppressor in ovarian cancer." (PMID 26169480, 2015). "For RNF43, basically every tumor-associated variant in the RING domain disrupts its function." (PMID 39674817, 2025). "At the primary tumor site, the RNF43-mutated group had significantly more right-sided patients than left-sided patients (left-sided: 24.47%, N=69; right-sided: 52.13%, N=147), and the RNF43 wild-type cohort data were contrary (left-sided: 54.30%, N=2034; right-sided: 22.02%, N=825)." (PMID 40860811, 2025). "RNF43 was mutated in 11% of samples, with frame shift deletions (61.5%) as the predominant event, alongside nonsense and missense mutations—indicative of its tumor suppressor role through truncating alterations." (PMID 40940930, 2025). "In addition to a high CpG island methylator phenotype, factors such as high microsatellite instability, BRAF/RNF43 mutations, consensus molecular subtypes, and high tumor mutational burden are also correlated with decreased mRNA expression of SATB2." (PMID 40636538, 2025). "The PI3K/AKT pathway regulates DNA methylation via phosphorylation of AKT, which might explain the hypermethylated phenotype present in our tumor samples with RNF43 hotspot variants." (PMID 38725616, 2024). "Notably, tumours with RTK/WNT pathway BRAF and RNF43 co-mutations had higher expression of BRAF and lower expression of RNF43 compared with wild-type tumours and tumours carrying mutations of only one gene." (PMID 39112715, 2024). "Additionally, mutations in RNF43, a tumor suppressor, were prominently enriched in the H. pylori-induced DNA damage response (DDR) in gastric epithelial cells." (PMID 37174714, 2023). "In addition, loss of RNF43 function induced resistance to PD-1 blockade even in neoantigen-rich tumours." (PMID 36732592, 2023). "Since the presence of KRAS and RNF43 mutations in IPMNs may predict future development of advanced neoplasia from PCLs, these PCLs should be closely monitored and treated with surgery and/or targeted therapeutics." (PMID 35229994, 2022). "We and others identified mutated RNF43 in tumor tissues of IPMN patients." (PMID 35229994, 2022). "RNF43 mutations were detected in both tumor-derived and plasma cfDNA-derived DNA samples." (PMID 36097219, 2022). "Interestingly, RNF43 mutations are shown to be associated with distinct tumor locations and subtypes." (PMID 35907983, 2022). "RNF43(ring finger protein 43) encodes a transmembrane E3 ubiquitin ligase that downregulates the Wnt/β-catenin pathway by ubiquitinating the Wnt receptor and exerting tumor suppressor activity." (PMID 35008235, 2021). "Importantly, combining phosphomimetic substitution with distant oncogenic RNF43 mutations (i.e. I48T and R127P) restores RNF43-mediated tumour suppression." (PMID 32934222, 2020).
tumor (continued). "In addition, our study identified multiple distinct inactivating mutations in RNF43 limited to unique tumor subclones, a pattern previously observed by our group and not shared by other genes in our whole exome sequencing analyses." (PMID 32796935, 2020). "However, the RNF43 gene is among the most frequently mutated gene in Wnt-dependent tumor types, such as CRC and endometrium cancer." (PMID 32245111, 2020). "Our careful analysis of missense mutations in RNF43 has provided significant insights into the operation of this tumour suppressor with three functional domains: the extracellular PA domain for interaction with Fzd or Rspo, RING domain for ubiquitination and a phospho-switch for functional control." (PMID 32934222, 2020). "Interestingly, increased WNT pathway activation is frequently observed in BRAF-mutated tumours due to loss-of-function mutations in RNF43 —an E3 ubiquitin ligase which mediates ubiquitination and degradation of the WNT receptor complex." (PMID 31412666, 2019). "Additionally, the expression level of RNF43 was significantly correlated with the stage of tumor: Low RNF43 expression was associated with a low histological differentiation, bigger tumor size, deeper invasion and advanced pTNM stage." (PMID 31248166, 2019). "RNF43 expression is associated with the prognosis of various cancers and enhances the sensitivity to immunotherapy, conventional anticancer drugs, and molecular-targeted drugs by affecting signal transduction, drug metabolism, and the tumor immune microenvironment." (PMID 41487817, 2025). "However, there is a lack of comprehensive pan-cancer analysis of the clinical value and genetic mutations of RNF43, and the exact roles of RNF43 in modulating cancer progression and tumor immune microenvironment are still largely unknown." (PMID 37848933, 2023). "Thus, RNF43 loss-of-function renders tumor cells dependent on secreted Wnt ligands for survival." (PMID 35676246, 2022). "Therefore, harnessing phospho-regulation of RNF43 might be a potential therapeutic strategy for tumours with RNF43 mutations." (PMID 32934222, 2020). "Several RNF proteins have established roles in tumour biology: RNF43 negatively regulates Wnt signalling and acts as a tumour suppressor in gastrointestinal cancers." (PMID 41457280, 2026). "Borealin overexpression enhances tumor growth and metastasis by downregulating the RNF43 and AXIN2 expression levels and activating β-catenin, thereby decreasing the survival rate of patients with hepatocarcinoma." (PMID 41487817, 2025). "Our studies suggest that RNF43 silencing by RCOR2 is an additional mechanism to diminish its tumor suppressor function in wild-type tumors." (PMID 40608411, 2025). "RNF43 is a tumor suppressor E3 ligase that negatively regulates WNT signaling by promoting the degradation of WNT receptors." (PMID 39851497, 2025). "Although our investigation focused on RNF43 in PDAC, our findings suggest the applicability of JPI-547 to other tumor types with RNF43 mutations." (PMID 40959288, 2025). "RNF43 is known for its role in malignant tumour progression because of its E3 ubiquitin ligase activity." (PMID 40490947, 2025). "In preclinical models, RXC004 reduced tumor growth and increased differentiation in Wnt-dependent RNF43-mutant pancreatic AsPC1 and HPAF-II and RSPO3-fusion SNU-1411 colorectal xenografts." (PMID 38612911, 2024). "RNF43 mutations have also been associated with aggressive tumor biology, and in BRAF mutated patient derived organoids, RNF43 mutations were recently suggested to have a key role in promoting metastasis in animal models." (PMID 38982444, 2024). "Despite their lower overall CNV load compared with iCMS2 tumours, several late CNV deletions correlated with shorter survival, while BRAF and RNF43 mutations were early events." (PMID 39112715, 2024).
tumor (continued). "The ring finger protein 43 (RNF43), known as a tumor suppressor, inhibits the Wnt pathway via the ubiquitination and degradation of Wnt receptors of the Frizzled (Fzd) family, located at the cell membrane." (PMID 38339403, 2024). "RNF43 plays the role of a tumor suppressor as one of the gatekeepers that prevents excessive Wnt signaling." (PMID 38383910, 2024). "Several mutations facilitate or activate the Wnt signal, reversing the RNF43 tumor suppressor function into an oncogene." (PMID 38383910, 2024). "In the BRAF and RNF43 tumours, co-occurring mutations were observed in ACVR2A (FDR-adjusted P = 0.06) in HM tumours, and AKT1 (FDR-adjusted P = 0.03) and TYRO3 (FDR-adjusted P = 0.08) in the nHM tumours." (PMID 39112715, 2024). "Together, these results suggest that loss of ZNRF/RNF43 elevates EGFR levels and signaling, promoting tumor development, sometime in conjunction with Wnt signaling activation and other times independent of Wnt signaling." (PMID 38260423, 2024). "In colon cancer xenografts with RSPO fusion genes and RNF43 mutated pancreatic and ovarian xenografts, ETC-159 markedly reduced tumor growth and prevented tumor recurrence." (PMID 38612911, 2024). "RNF43 is a tumor suppressor negatively regulating the Wnt signaling pathway by degrading the Wnt Frizzled-LRP5/6 complex." (PMID 38725616, 2024). "Conversely, human RNF43 117fs-overexpressing tumours grew similarly to control tumours, and PD-1 blockade was less effective against these tumours than against human RNF43 WT-overexpressing tumours." (PMID 36732592, 2023). "Microsatellite instabilities (MSI) and somatic mutations in BRAF and RNF43 were enriched in both CMS1 and right-sided tumours (FDRmol < 0.05, hypergeometric test)." (PMID 37666855, 2023). "Ring finger protein 43 (RNF43), a tumor suppressor and possible prognostic biomarker in ccRCC, has been identified in our recent studies." (PMID 36097369, 2023). "Genomic analysis indicated that RNF43 mutation affected the genomic characteristics of patients with BRAF mutation, including microsatellite instability (MSI), tumor mutation burden (TMB) and the proportion of common gene mutations." (PMID 37409251, 2023). "In order to fill this gap of information, we explored the tumor biological significance of RNF43 and LRP1B in a large and extensively characterized cohort of therapy-naive GC by immunohistochemistry." (PMID 36823311, 2023). "RNF43 expression was linked to the abundance of several immune cell types, including CD8+ T cells, B cells, and macrophages within the tumor immune microenvironment." (PMID 37848933, 2023). "We explored the clinicopathological significance and genetic mutation characteristics of RNF43, and the crosstalk between RNF43 expression and the abundance of immune cells and immune-related molecules in the tumor immune microenvironment." (PMID 37848933, 2023). "The correlations between RNF43, microsatellite instability (MSI), and tumor mutation burden (TMB) were also investigated." (PMID 37848933, 2023). "While the tumor suppressive effects of inactivating Pten, Rnf43, and Apc are consistent with previous data on these genes and/or related pathways in BRAF-driven lung cancer, the general decreases in magnitude relative to oncogenic KRAS were unexpected." (PMID 37828026, 2023). "In this study on a large and well-characterized cohort of GC patients, we explored the putative tumor biological significance of RNF43 and LRP1B." (PMID 36823311, 2023). "In support of this contention, in our series, the correlation between RNF43-expression and patient survival differed between the two tumor types." (PMID 36823311, 2023). "The tumor suppressive roles of RNF43 in different cancer types have been identified in multiple studies." (PMID 37848933, 2023). "We used the human RNF43 WT or 117fs-overexpressing CT26 cell lines, and compared with control tumours, human RNF43 WT-overexpressing tumours demonstrated reduced growth and improved response to an anti-PD-1 mAb." (PMID 36732592, 2023).
tumor (continued). "In PDAC, low RNF43 levels and an increased expression of frizzled receptors occurred, which promoted Wnt signaling activity and cell proliferation, leading to tumor transformation." (PMID 37304241, 2023). "RNF43 is a tumour suppressor gene that suppresses the WNT/β-catenin signalling pathway, and its RING domain plays a substantial role in its function." (PMID 36732592, 2023). "RNF43 and BRAF mutations are molecular events involved in serrated tumour pathways during CRC development." (PMID 37409251, 2023). "In Wnt-dependent cancers characterized by mutations in RNF43/ZNRF3 or by RSPO-fusions, WNTs provided by the tumor cells or the microenvironment are essential for tumor propagation." (PMID 36982422, 2023). "These and other antibodies have also been instrumental in immunohistochemical approaches to evaluate RNF43 protein expression in various tumor types." (PMID 37023034, 2023). "RNF43 mutations, commonly detected in CRC, enhance the sensitivity of tumor cells toward the porcupine inhibitor IWP2." (PMID 35985334, 2022). "Since the presence of RNF43 and KRAS mutations in IPMNs predicts future development of advanced neoplasia from PCLs, patients with these genetic anomalies warrant surveillance, surgery, and/or targeted therapeutics such as Wnt/β‐catenin inhibitors." (PMID 35229994, 2022). "The presence of inactivating mutations in RNF43, a negative regulator of WNT, in tumor cells predicts improved response rates and survival outcomes in patients with metastatic BRAFV600E colorectal cancer treated with anti-BRAF/EGFR therapy." (PMID 36097219, 2022). "Tumor staining in DDB2-knockout mice showed that the expression of the Wnt signaling inhibitor RNF43 (ring finger protein 43) decreased and the mRNA expression of the Wnt target gene Cdx1 increased." (PMID 36190612, 2022). "As shown by the heatmap, RNF43‐mutant PDAC tumor samples had a distinct cholesterol metabolic pattern as compared to RNF43‐WT samples." (PMID 35975457, 2022). "Further, we collected twelve primary PDAC tumor samples from patients, and identified two of these cases being RNF43‐mutant by whole‐exome sequencing." (PMID 35975457, 2022). "Molecular analysis indicated that the HCC tumours were indeed devoid of Rnf43/Znfr3 and expressed high levels of Axin2, confirming the Rnf43/Znrf3del origin of the tumour lesion." (PMID 35039505, 2022). "In summary, Rnf43 is a tumor suppressor in the prevention of pancreatic precancerous lesions and PDAC development." (PMID 35229994, 2022). "Mutation p.Gly659fs in the RNF43 gene, a hotspot mutation in MSI-H/dMMR tumours and component of the Wnt pathway, was broadly distributed in the cohort, but recent data have described no functional significance of this mutation in terms of pathway activation." (PMID 36613564, 2022). "In summary, our study identified a novel tumor suppressor, RNF43, which is also a prognostic indicator and potential target for ccRCC." (PMID 37304674, 2021). "Next generation sequencing analysis of the postoperative tumor tissue revealed that KRAS copy number was increased and detected SMAD4, RNF43, and PREX2 mutations." (PMID 34888240, 2021). "In the present study, we identified a novel tumor suppressor and prognostic indicator, RNF43, for ccRCC." (PMID 37304674, 2021). "Altogether, we provide evidence that RNF43 can act as a tumor suppressor and a negative regulator of the acquisition of the resistance to the targeted therapy." (PMID 34702444, 2021). "In contrast to the naïve and pazopanib-treated 786-O-PR groups, the pazopanib-treated 786-O-PR group with RNF43 overexpression showed slower tumor growth and a smaller tumor volume." (PMID 37304674, 2021).
tumor (continued). "Our results demonstrate that RNF43 is a novel tumor suppressor in ccRCC that inhibits YAP transcription and nuclear localization." (PMID 37304674, 2021). "Strikingly, in differential gene expression analysis of the TCGA dataset, RNF43 was the most differentially expressed gene between the two tumor groups (Padj = 4.6 × 10–15), with a -0.98 log2 fold decrease in mean expression level in APCmut– CRCs." (PMID 34873211, 2021). "Tumor sizes at end point for the RNF43 low cohort (N = 5) with RNF43 mid (N = 3), two-tailed t-test: *p=0.0297." (PMID 34702444, 2021). "Because deregulation of Wnt/β-catenin pathway promotes tumor formation, RNF43/ZNRF3 can act as tumor suppressors." (PMID 34702444, 2021). "Strikingly, Cle-H3 cells expressing RNF43(3SA) exhibited greatly accelerated anchorage-independent colony formation, spheroid formation and tumour growth in nude mice." (PMID 32934222, 2020). "Taken together, our results help to understand better the mode of RNF43 tumor suppressor action and solve some discrepancies present in the field." (PMID 32527265, 2020). "RNF43-mutant tumours were significantly enriched for right colonic distribution, BRAF mutations, microsatellite instability and CMS1 (MSI immune) classification, consistent with predominantly sessile serrated lesion aetiology." (PMID 31563876, 2020). "In this study, we uncover that the RNF43 C‐terminus performs an additional tumor suppressor role, by regulating the activity of the downstream β‐catenin destruction complex." (PMID 32965059, 2020). "Our findings further imply that WT RNF43 performs a bifunctional tumor suppressor role, mediating ubiquitin‐dependent Wnt receptor downregulation as well as ubiquitin‐independent regulation of destruction complex activity." (PMID 32965059, 2020). "RNF43 and ZNRF3 act as tumor suppressors and numerous mutations in the RNF43 gene were identified in cancers of various tissues, like endometrium, stomach, ovary, pancreases or colon." (PMID 32527265, 2020). "The aim was to segregate tumours into two clusters: LI tumours with identifiable mutations in APC or CTNNB1 and LD lesions with RSPO2/3 fusions or RNF43 alterations." (PMID 31563876, 2020). "The combined results thus indicate that RNF43 WT normally employs CK1 kinase activity to perform its tumor suppressor role." (PMID 32965059, 2020). "Having established the molecular ground truth, we segregated tumour samples in the discovery cohort into LD (RSPO-fusions, RSPO-high and RNF43 mutations, n=64) and LI (APC or CTNNB1 mutations, n=347) subsets." (PMID 31563876, 2020). "RNF43 acts as a tumor suppressor and negative regulator of Wnt/β catenin signaling, as well as non-canonical Wnt signaling." (PMID 32245111, 2020). "RNF43, as a transmembrane E3 ubiquitin ligase, downregulates the Wnt/β-catenin pathway by ubiquitinating the Wnt receptor frizzled; thereby, it exerts tumor-suppressor activity in the pathogenesis of IPMN." (PMID 32934653, 2020). "More recently, single-domain antibody fragments (VHH) against the WNT3-binding site have been shown to block Rnf43 mutant intestinal organoid growth and survival, by depleting stem-like tumor cells." (PMID 31412666, 2019). "Functional studies on RNF43 have shown that it acts as a tumor suppressor by negatively regulating Wnt signaling." (PMID 30884828, 2019). "The tumor suppressor function of RNF43 is based on its ability to inhibit Wnt signaling at the level of Frizzled (FZD) receptors as well as its capacity to sequester TCF4 to the nuclear envelope thereby disrupting transcription of Wnt target genes." (PMID 30884828, 2019). "The first set of four events involves three genes, FGF2, CCNE1, RNF43, whose tumor-specific APA regulations indicate clear length modulations of the 3’ UTR in cancer." (PMID 30005633, 2018).